SIGLEC5 (sialic acid binding Ig like lectin 5 )
Synonyms: CD170; CD33L2; OB-BP2; OBBP2; SIGLEC-5
Tractability: Antibody: its Gene Ontology location is reachable by antibodies, with high confidence; UniProt predicts a signal peptide or a membrane-spanning region.
Gene: Protein-coding gene on chromosome 19 (51,610,948 to 51,630,401, reverse strand). Ensembl gene ENSG00000268500.
Pathways (Reactome):
Immune System: Immunoregulatory interactions between a Lymphoid and a non-Lymphoid cell; Neutrophil degranulation
Gene Ontology:
Molecular function: protein binding; sialic acid binding
Biological process: cell adhesion
Cellular component: ficolin-1-rich granule membrane; plasma membrane; secretory granule membrane; tertiary granule membrane; membrane
Genetic constraint (gnomAD): Loss-of-function variants: 30 observed, 35.16 expected, observed/expected ratio (o/e) 0.85, 90% interval 0.64 to 1.16. The upper end of that interval is the gene's LOEUF score, 1.16, which puts it in group 5 of 6, group 1 being the genes least tolerant of losing a copy. Missense variants: 459 observed, 501.29 expected, observed/expected ratio (o/e) 0.92, 90% interval 0.85 to 0.99. Synonymous variants: 192 observed, 202.8 expected, observed/expected ratio (o/e) 0.95, 90% interval 0.84 to 1.07.
Homologues: Orthologues: chimpanzee SIGLEC5 (96% identical), macaque SIGLEC5 (87% identical), tropical clawed frog siglecl2 (26% identical), tropical clawed frog siglecl1 (24% identical), tropical clawed frog siglecl2 (23% identical), tropical clawed frog siglecl1 (16% identical). Paralogues in human: SIGLEC14 (55% identical), SIGLEC10 (48% identical), SIGLEC11 (47% identical), SIGLEC6 (42% identical), SIGLEC8 (42% identical), SIGLEC9 (40% identical), SIGLEC7 (39% identical), SIGLEC12 (39% identical), CD33 (34% identical), SIGLEC1 (27% identical), MAG (23% identical), SIGLEC16 (19% identical), and 4 more.
Diseases named in the same sentence as SIGLEC5 in open-access papers:
SIGLEC5 is named in the same sentence as 24 diseases in open-access papers, as found by Europe PMC text mining. Sharing a sentence is not in itself a finding about the gene and the disease. The quoted sentences say what the papers report.
periodontitis (13 papers, 2019 to 2025). An acute or chronic inflammatory process that affects the tissues that surround and support the teeth. "MAFB is suggested to be associated with the activation of SIGLEC5 expression and contribute to early-onset periodontitis." (PMID 39240858, 2024). "Periodontitis risk attributed to the immune receptor gene SIGLEC5 is shown to act via impaired MAFB binding." (PMID 35860693, 2022). "These experiments indicated that MAFB regulation is linked with activation of SIGLEC5 expression and with increased risk for early-onset periodontitis." (PMID 34852650, 2022). "Recently, a genome-wide association study and 2 genome-wide association study meta-analyses found 2 associated regions (haplotype blocks) at the inhibitory immune receptor gene SIGLEC5 to increase the risk for periodontitis." (PMID 34852650, 2022). "Two large GWASs independently found genetic variants at SIGLEC5 to be associated with different forms of periodontitis, indicating broad relevance of this locus for the disease etiology." (PMID 34852650, 2022). "Increasing transcription of SIGLEC5 was predicted to associate with increasing odds of periodontitis/loose teeth (P = 8.7 × 10−07)." (PMID 31235808, 2019). "We, therefore, used four SNPs, in LOC107984137, MTND1P5, DEFA1A3, and SIGLEC5 loci, previously associated with periodontitis in GWAS, as instruments for making causal inferences about the role of periodontitis in human BP regulation." (PMID 31504461, 2019). "Interestingly, EZH1 and MRPS23 were newly identified, whereas previous studies have verified SIGLEC14 and SIGLEC5 as genetic risk factors for periodontitis." (PMID 36611863, 2022). "Additionally, a study that integrated expression quantitative trait locus (eQTL) data with GWAS associations implied SIGLEC5 as periodontitis risk gene." (PMID 34852650, 2022). "These are located at the genes SIGLEC5, DEFA1A3 and FCER1G, and those are associated with periodontitis at a genome‐wide significance level." (PMID 40197750, 2025). "Currently, the available dataset for GWAS related to early onset (grade C) periodontitis identified potentially predisposing variants in the genes of DEFA1A3, FCER1G and SIGLEC5 at the level of genome‐wide significance." (PMID 40197750, 2025). "Genome-wide association studies showed the relationship of NIN, ABHD12B, WHAMM, AP3B2, and SIGLEC5 with chronic periodontitis." (PMID 36360171, 2022). "Further investigation of SIGLEC5 in periodontitis pathologies and intervention targeting the biological pathway underpinned by SIGLEC5 may contributes to both aetiology understanding and disease treatment." (PMID 39240858, 2024). "Because the underlying molecular mechanisms of periodontitis are still largely unclear, the effects of the NIN and SIGLEC5 genes on periodontitis have not been clarified, although significant associations with periodontitis were identified in the European population." (PMID 30765789, 2019). "Finally, we identified two previously reported genes (SIGLEC5, SIGLEC14) and two novel genes (EZH1, MRPS23), proving that TWAS is a supplemental strategy for studying periodontitis’ etiology." (PMID 36611863, 2022). "Since the underlying molecular mechanisms of periodontitis are still unclear, the effects of the NIN, ABHD12B, WHAMM, AP3B2, and SIGLEC5 genes on periodontitis have not been elucidated." (PMID 36360171, 2022).
colorectal cancer (5 papers, 2021 to 2023). A primary or metastatic malignant neoplasm that affects the colon or rectum. "In a cohort of 114 patients with colorectal cancer, our data confirmed the relevance of soluble SIGLEC5 levels as a prognosis marker and exitus predictor." (PMID 34359797, 2021). "Soluble SIGLEC5 has also been identified as a prognostic marker in colorectal cancer patients." (PMID 37465100, 2023). "Furthermore, SIGLEC-5 is upregulated in several types of tumors, including glioma and colorectal cancer and has been proposed as a prognosis marker to predict patient outcome." (PMID 37854605, 2023). "Finally, SIGLEC5 is suggested as a prognostic marker for colorectal cancer but we found no previously published association with ovarian cancer." (PMID 35406529, 2022). "Additionally, the role of SIGLEC5 as an immune evasion molecule in colorectal cancer was evaluated." (PMID 35884505, 2022).
glioma (3 papers, 2021 to 2023). A benign or malignant brain and spinal cord tumor that arises from glial cells (astrocytes, oligodendrocytes, ependymal cells). "In THP-1 cells grown in the presence of U87MG glioma, the exposure to Dex or TMZ caused decreased SIGLEC5 transcripts levels, but increased expression of SIGLEC14." (PMID 33670244, 2021). "In a recent work, the authors characterized the expression of Siglec5, 7, 9 on MDSC both from peripheral blood and glioma infiltrating cells and found the respective ligands both on GB cell lines and patient-derived glioma tissue samples." (PMID 35682991, 2022).
Sepsis (3 papers, 2021 to 2025). Sepsis is defined as life-threatening organ dysfunction caused by a dysregulated host response to infection. "The structure of SIGLEC5 exhibits strong similarities with that from well-known IC candidates, and it has recently been described as a patent IC candidate in sepsis." (PMID 35625783, 2022). "The SIGLEC5 structure exhibits strong similarities with that from well-known IC candidates, and it has recently been described as a patent IC candidate in sepsis." (PMID 34359797, 2021).
autoimmune disease (2 papers, 2022 to 2025). A disorder resulting from loss of function or tissue destruction of an organ or multiple organs, arising from humoral or cellular immune responses of the individual to their own tissue constituents. "For example, Asian-specific haQTLs provided novel candidate variants in gene loci associated with leprosy (SIGLEC5, TNFSF15) and autoimmune disease (CARD9, IRF5, IL27, FOS) (nd 48)." (PMID 35102304, 2022).
depression (1 paper, 2024). "As a result, we discovered 43 key genes associated with pain–depression comorbidity, along with the identification of RNF24, MGAM, FOS, TKT, and SIGLEC5 as hub genes." (PMID 39125922, 2024).
diabetes (1 paper, 2024). "Finally, the Mendelian randomization phenome-wide association study corroborated MANSC4 as a reliable target capable of mitigating the risk of various forms of diabetes, and it revealed the absence of adverse effects linked to CTRB1, SIGLEC5 and MST1." (PMID 38931433, 2024).
hearing loss (1 paper, 2025). "The discovery that methylation at the promoter regions of DNMT3A, UQCR11, POLQ, and SIGLEC5 has a protective effect against hearing loss suggests a multifaceted mechanism by which epigenetic regulation preserves auditory function." (PMID 40428348, 2025).
hypospadias (1 paper, 2020). Hypospadias is the displacement of the urethral meatus on the ventrum of the penis. "This region on chromosome 19 is characterized by clusters of sialic acid-binding Ig-like lectin (SIGLEC) and kallikrein (KLK) genes, among which we identified likely causal relationships with hypospadias (CD33/SIGLEC3, SIGLEC5, SIGLEC7, KLK5, KLK7, KLK10, KLK13, and KLK14)." (PMID 32728162, 2020).
neuroendocrine neoplasm (1 paper, 2025). Endocrine tumors, also referred to as neuroendocrine tumors (NETs), are defined by a common phenotype which is characterized by the expression of general markers (neuron specific enolase, chromogranin, synaptophysin) and hormone secretion products. "Therefore, SIGLEC5 might not only have a potential prognostic value in neuroendocrine neoplasms, but it could also be implicated in the mechanisms leading to malignant transformation and the resulting poorer clinical outcomes in these tumors." (PMID 40038821, 2025).
tumor (8 papers, 2020 to 2025). "The study also indicated the presence of tumor macrophages (CD68+CD163+CSF1R+SIGLEC5+) associated with immunotherapy resistance." (PMID 40404633, 2025). "KLRC1 and SIGLEC5 mediate immune activation and suppression, respectively, and are involved in tumor immune surveillance." (PMID 41438620, 2025). "In agreement, previous evidence suggested that blocking SIGLEC-5 could serve as a new immune checkpoint blockade strategy to enhance anti-tumor T cell functions." (PMID 37854605, 2023). "In addition, plasma levels of SIGLEC5 correlated with disease stage, tumor dedifferentiation and lymph node infiltration, all which point to its efficacy as a biomarker of CRC evolution." (PMID 34359797, 2021). "Among this receptor family, SIGLEC5 and its soluble form, soluble SIGLEC5 (sSIGLEC5), have been shown to bind the highly sialylated P-selectin glycoprotein ligand-1 (PSGL-1) molecule present on T lymphocytes, promoting tumour progression." (PMID 35625783, 2022).
bacterial infection (1 paper, 2014). "For example, little is known about the role of SIGLEC5, a member of the Siglec family of sialic acid-binding lectins in host response to bacterial infection." (PMID 24912583, 2014).
infection (1 paper, 2019). The state of being infected such as from the introduction of a foreign agent such as serum, vaccine, antigenic substance or organism. "Binding to the inhibitory receptors Siglec‐3, Siglec‐5, Siglec‐9, and Siglec‐11 suppresses the pro‐inflammatory response, which could contribute to decreased clearance of infection and contribute to the relative paucity of symptoms." (PMID 30697344, 2019). "In fact, Siglec‐14 has been shown to counteract the exploitation of Siglec‐5 by GBS, and Siglec‐16 reduces survival of E. coli K1 during infection." (PMID 30697344, 2019).
SIGLEC5 also shares sentences with these, for which no sentence is quoted: cancer (2 papers); chronic periodontitis (2); COVID-19 (1); dental caries (1); ischemia (1); leprosy (1); melanoma (1); meningitis (1); ovarian carcinoma (1); Salmonella Infections (1); septic shock (1).